ENSG00000200706
Synonyms: LOC124901525
Gene: Small nucleolar RNA gene on chromosome 6 (38,207,274 to 38,207,345, forward strand). Ensembl gene ENSG00000200706.
Gene Ontology:
Biological process: RNA processing
Cellular component: nucleolus
Homologues: Orthologues: rat Snord45l1 (65% identical). Paralogues in human: SNORD45B (89% identical), SNORD45C (78% identical), SNORD45A (76% identical).